MYD88 (MYD88 innate immune signal transduction adaptor)
Diseases named in the same sentence as MYD88 in open-access papers (continued):
Sharing a sentence is not in itself a finding about the gene and the disease.
periodontitis (19 papers, 2015 to 2026). An acute or chronic inflammatory process that affects the tissues that surround and support the teeth. "Our results indicate that P.g-OMVs inhibit osteogenic differentiation of BMSCs via the SAA3-mediated TLR4/MyD88/NF-κB axis, providing novel targets for the treatment of periodontitis-induced alveolar bone loss." (PMID 40791819, 2025). "It inhibited the secretion of inflammatory factors and expression of the TLR/MyD88/NF-κB pathway caused by F. nucleatum to inhibit its inflammatory effect on GECs, which was validated in a mouse model of periodontitis." (PMID 37460552, 2023). "In a mouse model of periodontitis induced by P. gingivalis, the loss of MyD88 in TLR signaling significantly reduced the expression of GAS6, AXL, and PROS1." (PMID 34734092, 2021). "Our findings indicated that inhibition of P.g-OMVs release and targeting SAA3-mediated TLR4/MyD88/NF-κB axis could be possible strategies to rescue periodontitis-induced alveolar bone loss." (PMID 40791819, 2025). "Our study suggests that targeting P.g-OMVs release or SAA3/TLR4/MyD88/NF-κB axis may be an effective strategy to rescue periodontitis-induced alveolar bone loss." (PMID 40791819, 2025). "The data show that pharmacological inhibition of MYD88 suppresses osteoclast induction and alveolar bone resorption caused by periodontitis in vivo, thereby suggesting that MYD88 can be a therapeutic target for bone loss due to bacterial infections, including periodontitis." (PMID 36333322, 2022). "Systemic administration of an MYD88 inhibitor prevents jawbone loss in Pg-driven periodontitis." (PMID 36333322, 2022). "In this study, we hypothesized that the expression of TLR4 or TLR4-associated molecules such as CD14, MD-2 and MyD88 are regulated by periodontitis and T2DM." (PMID 26581717, 2015). "In this study, IHC assays further demonstrated that P. gingivalis increased Tlr2, Tlr4 and Myd88 expression in P. gingivalis-induced mouse periodontitis compared with that in the controls." (PMID 40307566, 2025). "Recent studies have confirmed that DERL3 participates in the pathogenesis of periodontitis by modulating the TLR4/MyD88 pathway through KAT3B-regulated succinylation modification." (PMID 41459503, 2025). "In periodontitis, lipopolysaccharide from Porphyromonas gingivalis, a key pathogen, activates NF-κB through the TLR4/MyD88/NF-κB pathway, and causes nuclear translocation of NF-κB, induces the upregulation of MyD88 and NF-κB gene expression." (PMID 36769328, 2023). "When using TLR4‐/‐ or Myd88‐/‐ mice to establish the periodontitis model, we find that CEJ to ABC distance is much lower than that of WT mice." (PMID 37647428, 2023). "In summary, this study demonstrates that NAC‐S2 inhibits various pro‐inflammatory cytokines and periodontitis in mouse model in TLR4/Myd88‐dependent manner." (PMID 37647428, 2023). "On the other hand, MYD88 was found to be differentially hypermethylated in leucocytes of patients with periodontitis but differentially over-regulated in the transcriptome of PBMCs." (PMID 36233348, 2022). "Moreover, periodontitis was associated with an enhanced production of TLR2, MyD88 and TGFβ, as well as higher activities of SOD and catalase antioxidant enzymes in the adipose tissue." (PMID 42037322, 2026). "The TLR4/MyD88 pathway is a well-established regulatory axis in periodontitis." (PMID 41459503, 2025). "All of these indicated the effect of NAC‐S2 on periodontitis was TLR4/Myd88 dependent." (PMID 37647428, 2023). "First, the effect of NAC‐S2 on periodontitis is achieved in a TLR4/Myd88‐dependent manner." (PMID 37647428, 2023). "The role of NAC‐S2 on periodontitis is TLR4/Myd88 dependent." (PMID 37647428, 2023). "We tested the therapeutic impact of an MYD88-specific inhibitor on periodontitis." (PMID 36333322, 2022). "In our periodontitis in vitro model, LPS-G augmented the expression of NFκB, MyD88, and p300." (PMID 33542783, 2021).
periodontitis (continued). "Since activation of the osteocyte MYD88 pathway is a significant cause of inflammatory osteolysis due to bacterial infection, targeting the MYD88 signaling and downstream RANKL regulatory mechanisms in osteocytes would be a treatment strategy for bone destruction in periodontitis and osteomyelitis." (PMID 36333322, 2022). "A periodontitis mouse model was established by ligating the subgingival between the first and second molars in wild‐type, TLR4‐/‐, and Myd88‐/‐ mice." (PMID 37647428, 2023). "At last, we determined the effect of NAC‐S2 on periodontitis mouse models that were established in WT mice, TLR4‐/‐ mice, and Myd88‐/‐ mice." (PMID 37647428, 2023). "In established chronic periodontitis mouse model, NAC‐S2 attenuated inflammatory response in TLR4/Myd88‐depedent manner." (PMID 37647428, 2023). "Hypermethylation was found in TLR regulators genes: MAP3K7, MYD88, IL6R, RIPK2, FADD, IRAK1BP1, and PPARA in early stages of periodontitis, while advanced stages presented hypomethylation of these genes." (PMID 36233348, 2022). "This study investigated the effects of T2DM and periodontitis on TLR4, CD14, MD-2 and MyD88 mRNA expression in surgically removed periodontal tissues." (PMID 26581717, 2015). "Our study demonstrates that NAC‐S2 could suppress the Toll‐like receptor 4 (TLR4)/Myd88‐dependent NF‐κB and IκB kinase (IKK) signaling pathways in periodontitis." (PMID 37647428, 2023). "More importantly, NAC‐S2 treatment shows no influence on CEJ to ABC distance in TLR4‐/‐ or Myd88‐/‐ mice periodontitis model." (PMID 37647428, 2023). "Periodontitis patients have significantly elevated levels of LY96, which leads to the formation of LY96-TLR4-CD14 complexes that trigger the myeloid differentiation factor-88 (MyD88) pathway, resulting in TNF-α, IL-6, IL-8, and IL-2 production in the gingival tissue." (PMID 39555084, 2024). "In wild‐type periodontitis mice, NAC‐S2 administration decreased the cemento‐enamel‐junction–alveolar bone crest (CEJ‐ABC) distance and the relative mRNA expression of TNF, IL‐6, and IL‐1β, while such phenomena could not be observed in TLR4 deficiency or Myd88 deficiency mice." (PMID 37647428, 2023). "To test our hypothesis, we collected periodontal tissues from patients with or without periodontitis and T2DM at the time of necessary surgeries and determined the mRNA expression of TLR4, CD14, MD-2 and MyD88 using quantitative real-time polymerase chain reaction (PCR)." (PMID 26581717, 2015).
Salmonella Infections (19 papers, 2004 to 2024). Infections with bacteria of the genus SALMONELLA. "For instance, the inability to control Salmonella infection due to defective toll-like receptor (TLR)/myeloid differentiation primary response 88 (MyD88) signaling has linked the development of persistent infections to a breakdown in B cell tolerance." (PMID 29973931, 2018). "A suppressive role for B cell-intrinsic MyD88 expression has also been proposed, which may well underlie the breakdown of B cell self-tolerance in our Salmonella infection model." (PMID 29973931, 2018). "(I) RT-qPCR analysis of mRNA levels of genes involved in nuclear factor kappa B (NF-κB) signaling (p65, MyD88, Ikkα, and Ikkβ) measured in BMDMs 60 min after Salmonella infection (n = 5)." (PMID 39475776, 2024). "Similar profiles of TLR4 and MyD88 in the piglet groups in the ileum and mesenteric lymph nodes attest to MyD88 as the main adaptor molecule mediated inflammatory signaling in the Salmonella infection." (PMID 36768650, 2023). "In the MLN, expression of CD14, TLR2, and MyD88 all increased in response to Salmonella-infection, except in piglets previously innoculated with the probiotic E. coli." (PMID 31847111, 2019). "In the salmonella infection signaling pathway, MYD88 and AP-1 were significantly up-regulated (P < 0.05 or P < 0.01) in REV infected cells compared with control cells by Q-PCR." (PMID 29410628, 2018). "Transcription of IFN-γ, the main cytokine that defines the Th1 signature, was significantly elevated (27- to 32-fold) upon Salmonella infection in both MyD88+/+ and MyD88−/− mice." (PMID 29973931, 2018). "Taken together, the data confirm that Salmonella infection of MyD88−/− mice induces significant levels of autoantibodies of multiple specificities." (PMID 29973931, 2018). "Here, we report a pleiotropic role for caspase-8 in the control of gene expression downstream of Yersinia and Salmonella infection, as well as all TLRs that we tested, including those that signal through MyD88." (PMID 27737018, 2016). "Even though DKO mice succumbed to Salmonella infection earlier than MyD88−/− mice, both strains had low serum IFN-γ and elevated IL-10." (PMID 26441965, 2015). "Conversely, B-cells also suppress T-cell activity as best illustrated in mice with a targeted deletion of MyD88 in B-cells during Salmonella infection." (PMID 23308074, 2012). "During Salmonella infection, mice with a targeted deletion of MyD88 in B-cells exhibited an accumulation of neutrophils in the spleen, an effect that likely depends on Bregs-mediated IL-10 production." (PMID 23308074, 2012). "Wild-type Salmonella infection activates NF-κB potently in both the wild-type and TLR deficient MEFs (lanes 2 & 15) but this activation is somewhat defective in the MyD88 deficient MEFs (lane 10)." (PMID 15324458, 2004). "of Osaka, JA) to verify the role of MyD88 and to examine the potential role of two of the TLRs to respond to flagellin or to direct wild-type Salmonella infection and lead to NF-κB activation." (PMID 15324458, 2004). "TLR4, MyD88, and interleukin (IL) 8 increase after Salmonella infection." (PMID 32075044, 2020). "We concluded that the signaling in the Salmonella infection was via the MyD88 regulatory pathway." (PMID 31847111, 2019). "Additionally, Salmonella infection induced significant elevation (2.5-fold) in serum BAFF levels in MyD88−/− mice compared to uninfected counterpart." (PMID 29973931, 2018). "MYD88 and AP-1 were involved in salmonella infection pathway." (PMID 29410628, 2018). "A recent study has shown that MyD88 signaling pathway is necessary for the activation of autophagy of intestinal epithelial cells following Salmonella infection and that defects in this signaling pathway contribute to impaired protection against bacterial invasion." (PMID 25010669, 2014).
Salmonella Infections (continued). "Considering the interconnection between innate and adaptive immune responses, the abnormal activation displayed by splenic myeloid cells of MyD88−/− animals suggested the possibility that Salmonella infection could also affect the activation of adaptive immune cells." (PMID 29973931, 2018). "Thus, B lymphocytes from MyD88−/− mice appear to be hyper-responsive to Salmonella infection." (PMID 29973931, 2018). "We focused on the expression of genes involved in the MyD88-TLR signaling pathway, Salmonella infection, and phagocytosis, respiratory burst, chemokine production, and neutrophil chemotaxis related to heterophil function." (PMID 36807561, 2023). "Salmonella infection, for example, can promote TLR4/ MyD88 pathway activation and consequent increases in macrophage and neutrophil infiltration." (PMID 35123464, 2022). "The MyD88-dependent TLR signaling pathway is critical for regulating NF-κB signaling and innate immune response in Salmonella infection." (PMID 34067819, 2021). "The splenic niche of MyD88−/− mice revealed increased counts of activated, Sca-1-positive, myeloid subpopulations highly expressing BAFF during persistent Salmonella infection." (PMID 29973931, 2018). "Overall, our data revealed that synergistic effects of CD40 and MyD88 do not influence host survival to Salmonella infection or serum levels of IFN-γ or IL-10." (PMID 26441965, 2015). "Overall, our data using mice with a single or double deficiency in MyD88 and CD40 revealed that synergistic effects of CD40 and MyD88 do not influence host survival to Salmonella infection, CFUs in infected tissues or serum levels of IFN-γ or IL-10." (PMID 26441965, 2015). "We believe that the MyD88-dependent signaling pathway is the crucial pathway in the case of the ileum and in the case of the colon, but the downregulation of the TRIF-dependent pathway by Salmonella infection and its relation to the LPS chain needs future studies." (PMID 38003758, 2023). "After Salmonella infection, the amount of IL-4 and IL-21 was strongly upregulated in CD4+ T cells of MyD88−/−, but not MyD88+/+, mice." (PMID 29973931, 2018).
Hepatic steatosis (18 papers, 2014 to 2025). Steatosis is a term used to denote lipid accumulation within hepatocytes. "MyD88 deletion increases the risk of developing type 2 diabetes and hepatic steatosis in animals fed with a high-fat diet (HFD)." (PMID 38291436, 2024). "In this study, we used HSCs/myofibroblasts-specific MyD88-deficient mice and found that specific deletion of MyD88 in HSCs/myofibroblasts attenuated hepatic steatosis, inflammatory cell infiltration, and adipogenesis in an HFD-induced NAFLD mouse model." (PMID 38291436, 2024). "Moreover, we evaluated the impact of MyD88 deficiency in hepatic steatosis in PM2.5-exposed, HF-fed animals." (PMID 29176715, 2017). "The results of this study showed that it inhibited p65 nuclear translocation and NF-θB DNA-binding activity and that it decreased the expression of myeloid differentiation factor 88 (MyD88) in the liver, which, in turn, decreased hepatic steatosis." (PMID 39061866, 2024). "In alcohol-fed rats, scopoletin regulates AMPK and the toll-like receptor 4 (TLR4)/myeloid differentiation major response gene 88 (MyD88)/NF-κB pathway and alleviates alcoholic hepatic steatosis and inflammation." (PMID 38464713, 2024). "These events lead to the activation of the MyD88-NF-κB signaling pathway and promote inflammatory cytokine secretion in both humans and mice with fatty liver disease." (PMID 34956171, 2021). "While PM2.5 exposure relieved hepatic steatosis in HF-fed WT mice, the anti-hepatic steatosis effect of PM2.5 exposure was diminished in the HF-fed MyD88 KO mice." (PMID 29176715, 2017). "During HFD-feeding IEC MyD88-KO mice exhibited a lower body weight, fat mass gain and hepatic steatosis, despite similar energy intake and energy absorption." (PMID 25476696, 2014). "Additionally, the mucosal TLR4-induced MYD88 signaling pathway contributes to the development of hepatic steatosis." (PMID 33656663, 2021). "In disagreement with our study, a previous study has reported that PM2.5 exposure for 10 weeks relieved hepatic steatosis in high-fat diet-induced obese mice through inducing hepatic autophagy in livers in a manner depending on the MyD88-mediated inflammatory pathway." (PMID 30921449, 2019). "However, oil-red O staining of hepatic lipids indicated that MyD88 KO mice exhibited hepatic steatosis even under FA exposure, although PM2.5 exposure further exacerbated hepatic steatosis in MyD88 KO mice." (PMID 29176715, 2017). "The current study revealed that the specific deletion of MyD88 in HSCs/myofibroblasts attenuated DEN/HFD-induced hepatocarcinogenesis, hepatic steatosis, cell proliferation, and lipogenesis." (PMID 38291436, 2024). "In a high-fat- and high-cholesterol-diet-induced murine fatty liver disease, dietary advanced glycation end-product (AGE) activates the MyD88-NF-κB signaling pathway in KCs by upregulating the receptor for AGE (RAGE)." (PMID 34956171, 2021). "Our current work demonstrated a novel mechanism of curcumin in preventing HFD-induced hepatic steatosis, i.e. to reduced gut-derived endotoxin translocation and hepatic TLR4/MyD88/NF-κB signaling pathway." (PMID 31788011, 2019). "As MyD88 is required for PM2.5-triggered hepatic autophagy, we evaluated whether the counteractive effect of PM2.5 on hepatic steatosis relies on MyD88." (PMID 29176715, 2017).
tuberculosis (17 papers, 2011 to 2024). A chronic, recurrent infection caused by the bacterium Mycobacterium tuberculosis. "Thus, the present study aimed to investigate the association of MYD88 genetic polymorphisms with tuberculosis in a Caucasian population." (PMID 28127112, 2016). "TLR4 is expressed on both cytoplasmic and endosome membranes and signals through TRIF- and MYD88-dependent pathways, thereby facilitating immunosurveillance against tuberculosis." (PMID 37813638, 2023). "Mycobacterial components are known TLR2 and TLR4 agonists, and MyD88 dependent signaling is necessary to prevent lethality in response to infection to tuberculosis." (PMID 35921962, 2022). "Among the TLR family, TLR2, TLR4, and TLR9 and their adaptor molecule MyD88 play the most prominent roles in the initiation of the immune response against tuberculosis." (PMID 21603213, 2011). "Our study affirms that truncated TLR-MyD88 axis in HIV MDSC increases mycobacterial load, which potentially amplifies the risk of tuberculosis in HIV patients with virologic suppression; reconstituting MyD88 partially recovers mycobactericidal activity of HIV MDSC." (PMID 33995365, 2021). "Therefore, we dissected which MyD88-dependent pathways are essential for successful immunization with a tuberculosis subunit vaccine." (PMID 23308247, 2013). "Mtb-infected macrophages express Socs3 in a MyD88-dependent manner and during experimental tuberculosis (TB), Socs3 is induced in lungs of infected mice." (PMID 29176982, 2017). "The second network was tuberculosis (P = 1.03E−03), including ATP6V1H, cathelicidin 1 (CATHL1A), CTSS, ITGB2, myeloid differentiation primary response protein MyD88 (MYD88), and RAB5A." (PMID 30514405, 2018). "This possibility could explain, at least in part, the well described increased risk of infection and tuberculosis in patients with silicosis.In this study, we did not formally demonstrate that fibrosis in absence of MyD88 only results from T reg-related pro-fibrotic activities." (PMID 25050810, 2014). "Anti-tuberculosis drugs activated the TLR4–NF-κB–MyD88 pathway to induce liver injury, and high-dose Lc intervention inhibited the activation of NF-κB and MyD88 proteins, thus reducing oxidative stress and inflammatory response, as well as alleviating liver injury." (PMID 37298396, 2023). "During tuberculosis activation, miR-30 may suppress toll-like receptor/myeloid differentiation factor 88 (TLR/MyD88) activation and cytokine production." (PMID 35128217, 2022). "While some data suggests that Myd88 pathways may not be as critical in transition to adaptive defense against tuberculosis, more recent studies suggest that subversion of the TLR-2-MyD88 pathway is an important factor in intracellular processing." (PMID 26788020, 2015).